NCBP1 (nuclear cap binding protein subunit 1)
Diseases named in the same sentence as NCBP1 in open-access papers:
NCBP1 is named in the same sentence as 33 diseases in open-access papers, as found by Europe PMC text mining. Sharing a sentence is not in itself a finding about the gene and the disease. The quoted sentences say what the papers report.
lung carcinoma (10 papers, 2012 to 2025). "Given that CUL4B is an important ubiquitination‐related molecule, along with the fact that NCBP1 promotes the proliferation, migration and wound healing ability of lung cancer cells, we attempted to elucidate the underlying regulatory mechanism of CUL4B mediated by NCBP1." (PMID 31448526, 2019). "Nuclear cap-binding protein 1 (NCBP1) is require for capped RNA synthesis and is able to mediated proliferation, migration and invasion by participate in transcriptional and post-transcriptional processes and, it has been shown that NCBP1 to be associated with survival in lung cancer patients." (PMID 37185598, 2023). "NCBP1 (Nuclear Cap Binding Protein Subunit 1) is a recently confirmed protein-coding gene that has been connected to a wide variety of diseases, including lung cancer." (PMID 40177651, 2025). "Expression of this gene has been found to promote lung cancer growth and poor prognosis, and NCBP1 is overexpressed in basal-like and triple-negative breast cancers." (PMID 36199081, 2022). "A significant overexpression of NCBP1 was discovered in lung cancer tissues and NCBP1 promoted cancerous cells’ growth, wound healing capacity, migration, and epithelial-mesenchymal transition." (PMID 36118897, 2022). "Bioinformatics analysis of The Cancer Genome Atlas (TCGA) dataset showed that NCBP1 and NCBP2 are highly expressed in lung cancer tissues and their expression levels are associated with poor prognosis." (PMID 35818360, 2022). "For the first time, we found that NCBP1 expression was significantly higher in lung cancer tissue than in non‐cancerous lung tissue." (PMID 31448526, 2019). "Using quantitative RT‐PCR and immunoblotting, we compared NCBP1 expression in 40 paired specimens of lung cancer tissue and adjacent normal lung tissue." (PMID 31448526, 2019). "Through knockdown and overexpression experiments, we showed that NCBP1 promoted lung cancer cell growth, wound healing ability, migration and epithelial‐mesenchymal transition." (PMID 31448526, 2019). "Using the TCGA data set, we found that expression of CUL4B mRNA was significantly correlated, albeit moderately, with that of NCBP1 in lung cancer tissue (r = .32; P < .0001)." (PMID 31448526, 2019). "In this study, we found that NCBP1 was significantly overexpressed in lung cancer tissues and several lung cancer cell lines." (PMID 31448526, 2019). "Overexpression of NCBP1 increased the proliferation, migration and wound healing of lung cancer cells, whereas the silencing of NCBP1 expression inhibited these functions." (PMID 31448526, 2019). "We used two lung cancer cell lines with NCBP1 knockdown and overexpression to systematically address the role of NCBP1 in the proliferation and migration of lung cancer cells." (PMID 31448526, 2019). "To further evaluate the role of NCBP1 in lung cancer tissues, we compared mRNA expression in 515 LUADs and 59 adjacent normal tissues from the TCGA data set." (PMID 31448526, 2019). "To examine the role of CUL4B as a mediator of the action of NCBP1 in lung cancer, we measured the viability of lung cancer cell lines with various combinations of plasmid transfections." (PMID 31448526, 2019). "In addition, one researcher extensively investigated the function of NCBP1 in lung cancer cell proliferation and migration using two lung cancer cell lines with NCBP1 knockdown and overexpression." (PMID 36998056, 2023). "Furthermore, suppression of NCBP1 expression markedly reduces cell growth and motility of lung cancer cells." (PMID 35818360, 2022). "Overexpression of NCBP1 and NCBP2 are associated with lung cancer progression." (PMID 35818360, 2022). "To test the effects of NCBP1 in vivo, we established a mouse lung cancer xenograft model." (PMID 31448526, 2019). "The expression of NCBP1 correlates with poor survival from lung cancer." (PMID 31448526, 2019).
lung carcinoma (continued). "Therefore, we conducted the present study to examine the expression of NCBP1 in lung cancer tissue and investigated the candidate target RNA, which mainly regulates tumorigenesis of lung cancer, to gain some insights into the possible mechanisms of NCBP1 involvement in lung cancer pathogenesis." (PMID 31448526, 2019). "NCBP1, a partner of NCBP2, promotes proliferation, migration, and wound healing of lung cancer cell lines." (PMID 35818360, 2022). "To further explore the relationship between NCBP1 and CUL4B expression, we measured CUL4B protein expression in lung cancer lines with and without overexpression or knockdown of NCBP1." (PMID 31448526, 2019). "In this research, we found that CUL4B expression correlated with that of NCBP1 in lung cancer tissue and in cancer cell lines, and cotransfection with CUL4B plasmids partially reversed the effects of NCBP1 silencing on lung cancer cell line proliferation, migration and wound invasion." (PMID 31448526, 2019). "Taken together, these data suggest that NCBP1 mediates, at least in part, the proliferation, migration and invasion characteristics, as well as EMT, in lung cancer cells, and that CUL4B may be a downstream mediator of the effects of NCBP1." (PMID 31448526, 2019). "Interestingly, NCBP1 is required for capped RNA synthesis and intracellular translation, and has recently been discovered to interact with NCBP3 to induce CUL4B expression, promote lung cancer cell growth, wound healing, migration, and epithelial-mesenchymal transition." (PMID 35982949, 2022).
breast carcinoma (4 papers, 2012 to 2024). "For example, we identified two variants, rs7872034 (missense variant in SMC2) and rs143745791 (missense variant in NCBP1), suggestively associated with a diagnosis of at least one breast cancer (plus any other cancer) versus no cancer." (PMID 36199081, 2022).
glioma (3 papers, 2022 to 2023). A benign or malignant brain and spinal cord tumor that arises from glial cells (astrocytes, oligodendrocytes, ependymal cells). "Western blot analysis showed that the protein expression levels of EIF4E2 and NCBP1 were significantly elevated in glioma tissues compared to matched healthy brain tissues." (PMID 36998056, 2023). "The respective expression levels of NCBP1 and EIF4E2 proteins were lower and remarkably elevated in glioma tissues compared to the relatively healthy brain tissues, as per a Western blot analysis of 10 LGG tissues and 10 healthy brain tissues." (PMID 36998056, 2023). "Immunohistochemistry analysis showed that EIF4E, EIF4E3, and NCBP2 were increased in lower-grade glioma tissues, while lower-grade glioma did not cause a significant difference in EIF4E2 and NCBP1 proteins." (PMID 36998056, 2023). "In contrast, immunohistochemical analysis of 10 refractory epilepsy tissues and 10 lower-grade gliomas (WHO grade II-III) tissues showed that lower-grade gliomas did not significantly increase in EIF4E2 and NCBP1 protein expression, while EIF4E, EIF4E3, and NCBP2 were increased." (PMID 36998056, 2023).
lung adenocarcinoma (3 papers, 2019 to 2024). A carcinoma that arises from the lung and is characterized by the presence of malignant glandular epithelial cells. "The abnormal expression of NCBP1 was observed in lung adenocarcinoma and diffuse large B‐cell lymphoma." (PMID 38071502, 2024). "Furthermore, elevated NCBP1 expression correlated with a poor prognosis in patients with lung adenocarcinoma, based on data from the TCGA database, but unfortunately, we lacked clinical survival data." (PMID 31448526, 2019). "In lung adenocarcinoma, we found that high expression levels of LARP1 are correlated with poor survival and nuclear cap-binding protein 1 (NCBP1)." (PMID 35982949, 2022).
viral infection (3 papers, 2007 to 2025). "NCBP1 has been reported to play a crucial role in viral infections by interacting with viral mRNA and influencing antiviral responses." (PMID 40431638, 2025). "Lastly, NCBP1 (P10) is involved in splicing and translation regulation and decay and nuclear mRNA export out with particular importance in cellular stress situations, such as viral infection." (PMID 38025266, 2023).
ovarian carcinoma (2 papers, 2012 to 2022). A malignant neoplasm originating from the surface ovarian epithelium. "Similarly, BRCA1/2 germline variants are prevalent among these subtypes; however, in our study populations, BRCA1/2 carriers were more common among those with an additional ovarian cancer whereas NCBP1 carriers more frequently had an additional cervical cancer." (PMID 36199081, 2022).
adrenal cancer (1 paper, 2024). A carcinoma involving a adrenal gland. "Furthermore, there exists a correlation between the expression of NCBP1 and the infiltration of immune cells in adrenal cancer and osteosarcoma." (PMID 38071502, 2024).
COVID-19 (1 paper, 2022). A disease caused by infection with severe acute respiratory syndrome coronavirus 2. "Furthermore, we observed that the major transcript of multiple genes switched to a different transcript (isoform switching) between COVID-19 patients and controls, such as IL2, IL34, SERPINE2, NCBP1, HRAS, PRPF6, NCBP2, and LUC7L2." (PMID 35421082, 2022). "Of note, we observed numerous DTU genes involved in RNA splicing, with 10 genes (e.g. HNRNPC, SNRPD3, QKI, and LUC7L2) increased major transcript usage and 18 genes (e.g. SNRNP48, NCBP1, CELF2, RALY, and PABPC1) decreased major transcript usage in the COVID-19 patients." (PMID 35421082, 2022).
hepatocellular carcinoma (1 paper, 2026). A malignant tumor that arises from hepatocytes. "Notably, NCBP1, PRPF8, and SNRPD1 were dependent genes in both CRC and hepatocellular carcinoma." (PMID 41195591, 2026).
liver cancer (1 paper, 2023). An epithelial or non-epithelial malignant neoplasm that arises from the liver. "Among the genes associated with the prognosis of liver cancer, the genes associated with shorter survival period are AGO2, DCPS, IFIT5, LARP1, NCBP2, NUDT10, and NUDT16; the genes associated with longevity are EIF4E3, EIF4G3, METTL1, NCBP1, NSUN2, NUDT11, NUDT4, and WDR4." (PMID 36845384, 2023).
lung adenoma (1 paper, 2019). A benign, well circumscribed epithelial neoplasm that arises from the bronchus or the lung parenchyma. "We used Kaplan‐Meier analysis to compare the predicted survival of lung adenoma (LUAD) patients (data from the TCGA database) with high expression of NCBP1 (n = 127) with that of patients with low/medium expression of NCBP1 (n = 375)." (PMID 31448526, 2019).
lung squamous cell carcinoma (1 paper, 2023). "In addition, SLC46A2, ZNF367, AC107214.1 and NCBP1 genes were identified as survival-related genes of patients with lung squamous cell carcinoma." (PMID 37185598, 2023).
mental disorder (1 paper, 2020). A disease that has its basis in the disruption of mental process. "In addition, we demonstrated that the spliceosome, never directly implicated in mental disorders previously, was a substantially neuronal function disrupted by gut microbiota dysbiosis, and the NCBP1 phosphorylation was identified as a novel pathogenic target." (PMID 33051451, 2020). "In addition, we demonstrated that the spliceosome, never directly implicated in mental disorders previously, was a significantly neuronal function disrupted by gut microbiota dysbiosis, and the NCBP1 phosphorylation was identified as a novel pathogenic target." (PMID 33051451, 2020). "In addition, the spliceosome, never directly implicated in mental disorders before, was a significantly perturbed neuronal functional element affected by gut microbial dysbiosis, and the NCBP1 phosphorylation was inferred as a novel-specific pathogenic target." (PMID 33051451, 2020).
non-small cell lung carcinoma (1 paper, 2022). A group of at least three distinct histological types of lung cancer, including non-small cell squamous cell carcinoma, adenocarcinoma, and large cell carcinoma. "NCBP3 may act as a bridge between RBPs in the biological function of mRNA, upregulating the expression of downstream target genes in non-small cell lung cancer by interacting with NCBP1, thereby promoting the progression of lung cancer." (PMID 36335189, 2022).
renal cell carcinoma (1 paper, 2025). "Further study has shown that METTL3, along with METTL4, METTL14, NCBP1, and WTAP, may interact to impact cell cycle, renal cell carcinoma, and pathways that are included in cancer and hence may influence CRC growth." (PMID 40177651, 2025).
sarcoma (1 paper, 2023). A usually aggressive malignant neoplasm of the soft tissue or bone. "Risk score = (0.1472) *EIF4A1 + (0.4087)*EIF4G3 (−0.2538)*NCBP1 + (0.6578)*WDR4 was applied to the calculation of OS in sarcoma patients." (PMID 36816047, 2023). "Sarcoma patients were divided into two groups according to the risk scores, survival status, and the expression of EIF4A1, EIF4G3, NCBP1, and WDR4." (PMID 36816047, 2023). "Moreover, AGO2, EIF4G3, NCBP1, and WDR4 were potential risk factors for DSS in sarcomas." (PMID 36816047, 2023). "Theoretically, miRNAs that bind to high expression EIF4A1, EIF4G3, NCBP1, and WDR4 should be down regulated in sarcomas and show poor prognosis." (PMID 36816047, 2023). "Patients with sarcoma who had high levels of EIF4A1, EIF4G3, NCBP1, and WDR4 exhibited a lower OS rate." (PMID 36816047, 2023). "TMB and MSI scores of sarcomas were dramatically enhanced with the increase of EIF4G3, NCBP1, and WDR4 expression according to our findings." (PMID 36816047, 2023). "The correlation between the expression of prognostic m7GRGs (EIF4A1, EIF4G3, NCBP1, WDR4) and immune infiltration in sarcomas was investigated using the TIMER database and TCGA database." (PMID 36816047, 2023). "According to TIMER data, EIF4G3, and NCBP1 were negatively connected with CD4+ T cells and dendritic cells, however, EIF4A1 and WDR4 were not substantially correlated with immune cell infiltration in sarcomas." (PMID 36816047, 2023). "Besides, we constructed a prognostic model that consists of EIF4A1, EIF4G3, NCBP1, and WDR4 m7GRGs for predicting the survival likelihood of sarcoma patients." (PMID 36816047, 2023).
tumor (16 papers, 2019 to 2025). "This is an innovative idea for the molecular targeted therapy of DLBCL and a new understanding of NCBP1 in the tumor regulatory mechanism." (PMID 37244946, 2023). "The results showed that NCBP1 was expressed at significantly higher in tumor tissue than in inflammatory lymph nodes (P = 0.0029)." (PMID 37244946, 2023). "Based on the NCBP1 pivotal role of NCBP1 in pre-mRNA biogenesis, aberrant NCBP1 expression is involved in tumour pathogenesis." (PMID 37244946, 2023). "To measure the effects of NCBP1 overexpression and knockdown on tumour cell migration ability, we performed a migration assay." (PMID 31448526, 2019). "After 35 days, xenograft tumour volumes and weights were significantly lower in NCBP1‐silenced tumours than in control tumours (P < .01)." (PMID 31448526, 2019). "Our in vivo study showed that silencing of NCBP1 reduced tumour size as well as affecting the morphological and biochemical characteristics of the tumours and simultaneously decreasing CUL4B expression." (PMID 31448526, 2019). "We performed a wound assay to study the effects of NCBP1 on tumour cell invasiveness using a wound healing assay." (PMID 31448526, 2019). "NCBP1 was significantly more highly expressed in tumour tissue than in adjacent normal tissue at the mRNA level (P < .01), and at the protein level (P = .00065)." (PMID 31448526, 2019). "We then used immunohistochemistry (IHC) to measure NCBP1 expression in sections of patient tumour tissue samples and adjacent normal tissue." (PMID 31448526, 2019). "Tumours in which NCBP1 was silenced showed significantly lower levels of CUL4B mRNA expression (P < .01)." (PMID 31448526, 2019). "Furthermore, we found that METTL3 was significantly positively correlated, albeit moderately, with NCBP1 using linear regression analysis in DLBCL tumor tissues from the GEPIA data set (r = 0.7; P < 0.0001)." (PMID 37244946, 2023). "Notably, mRNA levels of LARP1, METTL1, WDR4, and NCBP1 were upregulated in tumor specimens." (PMID 40485623, 2025). "An elevated protein expression of EIF4E, EIF4G3, LARP1, METTL1, NCBP1, NUDT4, and NUDT11 was discerned in the carcinoma samples, whereas the WDR4 expression was comparable between the tumor and adjacent non‐tumorous tissues." (PMID 40485623, 2025). "Numerous studies have found that m7G regulator hub genes (EIF4E, EIF4E3, EIF4E2, NCBP1, and NCBP2) are crucial in tumor progression and metastasis." (PMID 36998056, 2023). "In tumor tissues, EIF4E and NCBP2 were highly expressed, while WDR4 and NCBP1 were moderately expressed." (PMID 35784919, 2022). "NCBP1 was significantly overexpressed in LUAD, combined with CUL4B, which promoted the proliferation, migration and invasion of tumor cells." (PMID 36091687, 2022). "Notably, miR-181b-5p and miR-877-5p acted as negative regulators of tumor-suppressor genes (e.g., HEY2, MCL2, HAND2), while miR-204-5p and miR-143-3p appeared to indirectly target oncogenes (e.g., RAB10, DR1, PTBP3, NCBP1)." (PMID 41009685, 2025). "Mainly, survival analyses showed that the same expression of SLC46A2, ZNF367, AC107214.1 and NCBP1 genes in the primary and LNM lesions can provides more potent prognostic information when no analyses of the primary tumor have been done." (PMID 37185598, 2023). "The protein expressions of METTL1, NSUN2, EIF4G3, LARP1, NCBP1, and NCBP2 were higher in tumor tissues than in normal tissues; however, the protein expressions of WDR4, EIF4E1B, and NCBP2L were negative in both tumor and normal tissues." (PMID 35785179, 2022).
cancer (11 papers, 2017 to 2025). A tumor composed of atypical neoplastic, often pleomorphic cells that invade other tissues. "Aberrant NCBP1 expression is involved in the pathogenesis of cancers, but little is known about NCBP1 in DLBCL." (PMID 37244946, 2023). "NCBP1 expression varied in established cancer cell lines, with the highest expression seen in H838 and H1299 cells." (PMID 31448526, 2019). "We then performed parallel experiments, looking at the role CUL4B in mediating the effects of NCBP1 on cancer cell migration." (PMID 31448526, 2019). "We found that NCBP1 was significantly more highly expressed in cancer cells than in HBE cells (P < .05)." (PMID 31448526, 2019). "The exact mechanism involved in NCBP1/‐3‐mediated metabolism of CUL4B mRNA and exploring this axis as an avenue for the development of new cancer therapeutics will be the subject of our further studies." (PMID 31448526, 2019). "Finally, the gene expression patterns of cancer cell lines from the Genomics of Drug Sensitivity in Cancer database were combined in order to comprehensively investigate the potential therapeutic benefit of the EIF4A1, EIF4G4, NCBP1, and WDR4 genes." (PMID 36816047, 2023). "Regarding rs143745791, germline variants in NCBP1 have not been previously associated with cancer; because it is rare (MAF < 0.2%), larger sequencing efforts may be necessary to identify variation in studies of individuals with a single cancer." (PMID 36199081, 2022).
infection (3 papers, 2007 to 2022). The state of being infected such as from the introduction of a foreign agent such as serum, vaccine, antigenic substance or organism. "To analyze the efficiency of cell-to-cell movement of PlAMV, we monitored the sizes of PlAMV-GFP infection foci in inoculated leaves of Col-0 and the ncbp-1 mutant." (PMID 28059075, 2017).
NCBP1 also shares sentences with these, for which no sentence is quoted: prostate carcinoma (4 papers); diffuse large B-cell lymphoma (2); epilepsy (2); cervical cancer (1); colorectal cancer (1); glioblastoma (1); gram-negative bacterial infections (1); HIV-1 infection (1); melanoma (1); neuritis (1); osteosarcoma (1); pancreatic cancer (1); triple-negative breast carcinoma (1); urinary bladder cancer (1).